ALDH1L2 (aldehyde dehydrogenase 1 family member L2)
Description:
Mitochondrial 10-formyltetrahydrofolate dehydrogenase that catalyzes the NADP(+)-dependent conversion of 10-formyltetrahydrofolate to tetrahydrofolate and carbon dioxide.
Synonyms: mtFDH; FLJ38508
Tractability: Small molecule: it belongs to a druggable protein family. PROTAC: ubiquitination databases record sites on it; its protein half-life has been measured.
Gene: Protein-coding gene on chromosome 12 (105,019,784 to 105,107,643, reverse strand). Ensembl gene ENSG00000136010.
Subcellular location: Mitochondrion
Subcellular location (Human Protein Atlas): Mitochondria
Pathways (Reactome):
Metabolism: Metabolism of folate and pterines
Gene Ontology:
Molecular function: formyltetrahydrofolate dehydrogenase activity; protein binding; aldehyde dehydrogenase (NAD+) activity; catalytic activity; oxidoreductase activity
Biological process: 10-formyltetrahydrofolate catabolic process; NADPH regeneration; aldehyde metabolic process; folic acid metabolic process; one-carbon metabolic process
Cellular component: extracellular exosome; mitochondrion; mitochondrial matrix; cytoplasm
Genetic constraint (gnomAD): Loss-of-function variants: 90 observed, 110.14 expected, observed/expected ratio (o/e) 0.82, 90% interval 0.69 to 0.97. The upper end of that interval is the gene's LOEUF score, 0.97, which puts it in group 4 of 6, group 1 being the genes least tolerant of losing a copy. Missense variants: 974 observed, 1,132.1 expected, observed/expected ratio (o/e) 0.86, 90% interval 0.81 to 0.91. Synonymous variants: 360 observed, 394.25 expected, observed/expected ratio (o/e) 0.91, 90% interval 0.84 to 1.
Homologues: Orthologues: chimpanzee ALDH1L2 (99% identical), macaque ALDH1L2 (99% identical), dog ALDH1L2 (96% identical), rabbit ALDH1L2 (96% identical), pig ALDH1L2 (96% identical), rat Aldh1l2 (94% identical), mouse Aldh1l2 (92% identical), guinea pig ALDH1L2 (90% identical), tropical clawed frog aldh1l2 (85% identical), zebrafish aldh1l2 (80% identical), Caenorhabditis elegans alh-3 (58% identical), Drosophila melanogaster CG8665 (58% identical), and 3 more. Paralogues in human: ALDH1L1 (72% identical), ALDH1A2 (27% identical), ALDH1B1 (27% identical), ALDH2 (27% identical), ALDH1A3 (27% identical), ALDH1A1 (27% identical), ALDH9A1 (21% identical), ALDH8A1 (19% identical), ALDH5A1 (19% identical), ALDH7A1 (16% identical), ALDH6A1 (16% identical), ALDH4A1 (15% identical), and 5 more.